CD47 (CD47 molecule)
Diseases named in the same sentence as CD47 in open-access papers (continued):
Sharing a sentence is not in itself a finding about the gene and the disease.
cancer (continued). "In patients who underwent surgical resection without adjuvant treatment, a positive CD47 expression was associated with a shorter RFS (p = 0.001) but not with cancer-specific survival (CSS)." (PMID 33917794, 2021). "Owing to decorating with Sirpα variants, engineered exosomes could target CD47-overexpressing cancer cells, regulate macrophage phagocytosis through disruption of CD47-Sirpα interaction and lead to innate and adaptive immune responses against cancer." (PMID 34576180, 2021). "Therefore, future studies examining CD47 ubiquitination to develop the most effective cancer treatment should consider the effect of related side effects on the prognosis of patients with cancer." (PMID 34943817, 2021). "Thus, function blocking antibodies and peptides to CD47 or its receptor SIRPα induce macrophage phagocytosis of live cancer cells in culture and in vivo, and are being developed as a potential treatment for multiple cancers." (PMID 34177884, 2021). "Therefore, macrophage checkpoints including CD47–signal regulatory protein-alpha (SIRPA) signaling are considered to play important roles in cancer surveillance." (PMID 33799989, 2021). "Notably, recent studies have indicated that CD47 expression appeared to vary among different types of cancers." (PMID 33765961, 2021). "Previous literature examining the impact of SIRP:CD47 signaling has primarily focused on host immunity in the context of cancer development; hence, little is currently known about how this pathway relates to pancreatic β-cell development and survival in the context of T1D pathogenesis." (PMID 34603322, 2021). "Since the higher expression of CD47 is believed to bestow cancer cells to evade phagocytic elimination by innate immune cells, targeting CD47 has become more intriguing option for a novel cancer treatment." (PMID 33765961, 2021). "CD47, on EVs in cancer patients, carries a “don’t eat me” signal; thus, CEVs might overexpress CD47 in their parent cancer cells to escape the phagocytosis and rapid clearance of macrophages in the serum." (PMID 34804956, 2021). "Finally, the combined blockage of both CD24 and CD47 confers an additive phagocytosis‐mediated cancer‐killing effect." (PMID 34363319, 2021). "Gal-9 triggered a prominent change in the phagocytic balance on cancer cells, with downregulation of CD47 and PS exposure that could drive neutrophil trogocytosis." (PMID 35052746, 2021). "The cancer cells cultured with MSCHigh expressed significantly lower levels of CD47 than those cultured with the monocytic cell line, reinforcing the hypothesis that stromal cells can act on the cancer cells to alter the function and phenotype." (PMID 34885111, 2021). "Increased CD47 expression by cancer cells helps them evade macrophage-mediated elimination." (PMID 34068752, 2021). "This is because A549 cells are one of the CD47-overexpressing cancer cell lines." (PMID 34189144, 2021). "Currently, novel antibodies inhibiting the interaction between SIRPα and CD47 are in preclinical phases, while other anti-CD47 antibodies such as AO-176 are currently under evaluation in clinical trials for the treatments of several types of cancers." (PMID 33854480, 2021). "Recently, it was found that CD47 is paradoxically upregulated in different cancers." (PMID 34349643, 2021). "A direct therapeutic potential could be obtained if the nanobodies can modulate the CD47-SIRPα interaction, resulting in enhanced phagocytosis of cancer cells." (PMID 34917090, 2021). "CD47 regulates physiological functions, including cell growth, cell migration, axon extension, cytokine production, and T-cell activation, as well as cancer cell proliferation, motility, and invasiveness." (PMID 33799989, 2021). "As the effect of CD47 is due to macrophages, it is possible to speculate that siCD47 therapy may be most suited to cancers of organs with high resident macrophage populations." (PMID 34688033, 2021).
cancer (continued). "Interestingly, the addition of anti-CD47 Ab or Sirpα-ex fusion protein enabled WT BMDMs to phagocytize cancer cells, but to a significantly lesser degree than Sirpα−/− BMDMs under the same stimulation." (PMID 34050181, 2021). "In addition to CD29 and CD98, we also decided to test the following antigens, due to their known functions that make them candidates to be widely expressed on the cancer cell lines: CD47, B2M, and Epithelial cell adhesion molecule (EPCAM)." (PMID 33690223, 2021). "Other pathways may govern immunological immunoresistance of CSCs in different cancer types: c-Myc upregulates the expression of the innate immune inhibitor CD47 and adaptive immune checkpoint molecule PD-L1." (PMID 33806296, 2021). "CD47 is involved in cancer cell metastasis and has a prominent role in endothelial migration." (PMID 34189144, 2021). "Many studies have reported that tumors evade macrophage phagocytosis and immune surveillance by activating the inhibitory signal via the ligation of SIRPα (which is expressed on phagocytes as a receptor) with CD47 (which is highly expressed on cancer cells as a ligand)." (PMID 34349643, 2021). "Targeting of the CD47-SIRPα axis is being tested in numerous cancer types." (PMID 34885111, 2021). "Indeed, the CD47-SIRPα axis has become a promising target in cancer immunotherapy, and anti-CD47 antibody is currently investigated for use in various solid tumors." (PMID 33422072, 2021). "We found CD47 positively connected to various functions in most cancer types." (PMID 34966389, 2021). "Interestingly, CD47 is a “don’t-eat-me signal” expressed by almost all cancer cells, preventing the phagocytic eradication of malignant cells by innate immunity surveillance." (PMID 34572776, 2021). "The overexpression of membrane CD47 (also known as integrin associated protein) is a potent “do not eat me” signal for macrophages and allows cancer cells to evade macrophage phagocytic activity." (PMID 34575416, 2021). "Moreover, a high CD47 expression is an immune escape mechanism observed in cancer cells, and anti-CD47 antibodies are under investigation as cancer immunotherapeutics." (PMID 34698067, 2021). "In many cancers, amplification and overexpression of c-myc has been observed; these are involved in inducing the expression of immune checkpoint molecules such as PD-L1 and CD47." (PMID 34359568, 2021). "Besides, in combination with SIRPα on the surface of macrophages, CD47 can send an antiphagocytic “Don’t eat me” signal to the immune system that helps cancer cells avoid immune surveillance." (PMID 34805154, 2021). "CD47 is down-regulated in Tamoxifen apoptotic treatment, in Withaferin A and Indole-3-Carbinol nutrigenomics treatments, while it is up-regulated in 11 different cancer types." (PMID 34439361, 2021). "CD47 is known to play a role in cancer cell’s immune escape." (PMID 34685548, 2021). "CD47 blocking can increase the efficiency of cancer cells clearance by macrophages." (PMID 34858184, 2021). "Cancer single-cell state atlas (CancerSEA) was used to evaluate functional role of CD47." (PMID 34966389, 2021). "Additionally, cancer cells always express a ‘don’t eat me’ molecule, CD47, that binds to the signal regulatory protein α (SIRPα) receptor on macrophages and inhibits phagocytic activity." (PMID 33649336, 2021). "The treatment of various cancers with CD47 monoclonal antibodies has also been validated." (PMID 33629544, 2021). "The results showed that CD47 played different roles in distinct types of cancer." (PMID 34966389, 2021). "Blocking the CD47–SIRPα axis disinhibits phagocytosis and impedes cancer growth." (PMID 34685548, 2021). "Thus, we were initially puzzled by reports that some cancer stem cells have elevated CD47 expression." (PMID 33925464, 2021). "Consequently, a number of CD47-targeting antibodies are in clinical trials of numerous cancers spanning both hematological malignancies and solid tumors." (PMID 34305918, 2021).
cancer (continued). "To explore how CD47 might affect different cancers, we used CancerSEA single-cell database to analyze the correlation of CD47 with 14 distinct functions in 14 types of cancer." (PMID 34966389, 2021). "Calreticulin binds to the low-density receptor-related protein-1 (LRP1) on the surface of macrophages and is the primary pro-phagocytic signal that counteracts CD47 in cancer cells, being essential for phagocytosis during the disturbance of CD47-SIRPα interaction." (PMID 34944878, 2021). "Overexpression of CD47 enables cancer cells to escape phagocytosis." (PMID 33629544, 2021). "Consequently, preventing CD47-SIRPα interactions removes this inhibitory check-point signal and enables the effective removal of cancer cells." (PMID 34201127, 2021). "The repetitive setbacks made the prospect of developing CD47 for cancer treatment very pessimistic." (PMID 34717705, 2021). "Remarkably, CpG promotes the engulfment of CD47+ cancer cells." (PMID 34572013, 2021). "In subsequent studies, evaluation of tumors by TSP1 immunostaining indicated that its expression was increased in the tumors re-sensitized to tamoxifen, thus indicating an interplay of TSP1, CD47 expression, and metabolic regulation on cancer therapy sensitivity." (PMID 33925464, 2021). "So, the surface CD47 on cancer cells and exosomes should be blocked for cancer immunotherapy." (PMID 34512146, 2021). "We next investigated CD47 expression based on cancer stages using GEPIA database." (PMID 34966389, 2021). "Solutions to optimize CD47-CAR-T cell therapy for different types of cancer should be warranted." (PMID 34189144, 2021). "CD47, a “don’t eat me” signal, is overexpressed on the surface of most cancer cells." (PMID 34503245, 2021). "Anti-CD47 therapy may be safer than T cell-directed therapy because phagocytosis of cancer cells by macrophages would limit cancer cell content leakage." (PMID 33741032, 2021). "CD47-SIRPα interaction is the first discovered ‘don’t eat me’ signal in cancer." (PMID 33919517, 2021). "It has been suggested that blockade of the SIRPα‐CD47 checkpoint may provide a potential new way to treat cancer." (PMID 33463049, 2021). "This suggests that TSP1 signaling mediated by CD47 may generally suppress cancer stem cells (CSC) and restore sensitivity to adaptive immune clearance." (PMID 33925464, 2021). "Thus, overexpression of c-myc is involved in the immune evasion of cancer cells through CD47 and PD-L1." (PMID 34359568, 2021). "The expression of CD47, which is a transmembrane protein, decreases in red blood cells as they age; this “self” marker has also been found to be upregulated in the majority of cancers." (PMID 33748077, 2021). "Thus, the CAR-T CD47 cells in this study, in addition to the effect of killing target cancer cells A549, also inhibited the expression of genes involved in metastasis." (PMID 34189144, 2021). "In this study, humanized CD47-CAR-T cells showed a potential in killing the A549 cancer cell lines." (PMID 34189144, 2021). "Cancer cells evade macrophage phagocytic activity by overexpressing CD47 Thus, blocking the CD47-SIRPα innate immune checkpoint can be therapeutically exploited to potentiate the killing property of myeloid cells towards cancer cells." (PMID 34572013, 2021). "Importantly, hypoxia stress modulates the expression levels for important molecular targets in cancer immunotherapy including PD-L1, HLA-G, CD47, and VISTA." (PMID 33422072, 2021). "Furthermore, in lung squamous cell carcinoma, but not lung adenocarcinoma, SLFN11 expression correlates with the expression of CD47 (a cell surface molecule that sensitizes cancer cells to radiotherapy and chemotherapy)." (PMID 34571887, 2021). "In fact, recent studies have suggested that expression of CD47 in cancer might vary among different cancer types." (PMID 33765961, 2021).
cancer (continued). "Finally, as novel immunotherapies, such as anti-CD47 agents, cancer vaccines, and CAR T-cell therapies, are introduced into clinical practice, we recommend careful prospective evaluation of their safety in combination with RT." (PMID 34359583, 2021). "Interestingly, “don’t eat-me signal” CD47 on cancer cells inhibits neutrophil trogoptosis via interaction with signal regulatory protein a (SIRPa), which provides mechanistic insight into the CD47-SIRPa checkpoint blockade." (PMID 34069602, 2021). "Meanwhile, novel drug carriers such as modified biomimetic nanoparticles have been explored in cancer therapy, which may be a novel pathway worthy to deliver the therapeutic CD47 mAbs." (PMID 34717705, 2021). "Therefore, blockage of the CD47/SIRPα axis is a successful strategy to target and limit cancer cells." (PMID 34093795, 2021). "In this review, we discussed the current SIRPα-CD47 axis-mediated cancer cell immune escape and immunotherapy, which could provide an effective antitumor strategy by the innate and adaptive immune response." (PMID 34512146, 2021). "Finally, therapeutic interest in the CD47/SIRPα axis has grown tremendously in recent years following the discovery that many cancers co-opt CD47 expression to evade antitumor immunity." (PMID 34197341, 2021). "In the current study, we identified that Gal-9 on the one hand sensitized carcinoma cells to immune recognition by increasing PS exposure within minutes as well as rapidly decreasing surface expression of the key “don’t eat me” signal CD47." (PMID 35052746, 2021). "Collectively, these results indicated that SF protein could be effectively expressed to block CD47 when cancer cells are infected with SG635‐SF." (PMID 31899582, 2020). "Given that CD47-SIRPα signaling enables malignant cells to avoid macrophage-mediated phagocytosis, the inhibition of the CD47-SIRPα signaling axis represents a promising therapeutic strategy for the treatment of cancer, and multiple CD47 targeted drugs have entered the clinical trials." (PMID 32082311, 2020). "CD47, a “don’t eat me” signal activated via an interaction with signal regulatory protein α (SIRPα) on innate immune cells such as macrophages and DCs, is regarded as an innate immune checkpoint in cancer." (PMID 33168028, 2020). "If CD47 controls Cdc42 expression in NSCLC cells, and Cdc42 in turn mediates the invasive phenotype of these cancer cells, then blocking CD47 or inhibiting Cdc42 expression may become a new method of inhibiting the metastasis of NSCLC cells." (PMID 32082311, 2020). "The discovery that CD47 expression is often increased on the surface of cancer cells, and CD47’s role as a ‘don’t eat me’ signal for phagocytes, have led to significantly heightened interests in the development of neutralizing antibody-based therapeutics targeting the CD47-SIRPα interaction." (PMID 33224442, 2020). "When GBM8401 and GL261 cancer cells were cultured with RQ for 48 h, CD47 was downregulated." (PMID 32020472, 2020). "It has been reported that MYC is a transcription factor for CD47 in cancer cells." (PMID 32296015, 2020). "The intrinsic growth potential by HER2 is conjugated with CD47-mediated extrinsic anti-phagocytosis, demonstrating a need of an integrated therapeutic approach to target multiple factors to eliminate resistant cancer cells in the combined modality of RT with immunotherapy." (PMID 32929084, 2020). "However, there are growing evidences that the blockade of CD47 ligation can induce cancer cell apoptosis." (PMID 32882841, 2020). "The CD47/SIRPα axis was also identified as an immune checkpoint inhibitor in cancer therapy." (PMID 32984001, 2020). "Such CD47-initiated proliferative events, especially its communication with growth factors in radioresistant cancer cells remains unclear." (PMID 32929084, 2020). "Moreover, drugs that antagonize the CD47-SIRPα pathway are under development; CD47 is a transmembrane protein both on normal and cancer cells." (PMID 32575899, 2020).
cancer (continued). "Additional research revealed that irradiation of HPV-positive cancer cells induces the reduction of CD47 (cluster of differentiation 47) expression, which stimulates phagocytosis via dendritic cells and results in immune-mediated cell death of HPV-positive cancer." (PMID 32005919, 2020). "Other cancer cell types which express high levels of CD47 can also be used in the assay." (PMID 32159928, 2020). "Hence, targeting the CD47-SIRPα signaling system is a promising strategy for cancer treatment, including NPC." (PMID 32149101, 2020). "In addition, CD47 blockade by SαV-C-NVs also stimulated the T cell-mediated devastation of cancer cells owing to the improved antigen presentation by macrophages and dendritic cells." (PMID 32999291, 2020). "Targeting the CD47-SIRPα signaling axis is the promising strategy for cancer treatment." (PMID 32411788, 2020). "Notably, we found that the co-cultures were already sufficient to trigger a decrease in macrophage SIRPα, and an increase in cancer cells CD47." (PMID 32231135, 2020). "Indeed, CD47 expressed by cancer cells inhibits phagocytosis through its interaction with signal regulatory protein-α (SIRPα) expressed by macrophages thus sending out a “do not eat me” signal." (PMID 32322199, 2020). "It targets high-Ep-CAM cancer cells and effectively knocks down both CD47 and PD-L1 proteins." (PMID 32677994, 2020). "M1-NVs and SαV-C-NVs could serve to repolarize TAMs towards M1 phenotype and block the CD47-SIRPα pathway, thus improving the phagocytosis of cancer cells by macrophages." (PMID 32999291, 2020). "The increased expression of CD47 and the ‘don't eat me’ signal released by CD47 could be observed in many different human tumors, indicating that the CD47–SIRPα pathway is a potential target for treatment of human malignant tumors." (PMID 31899582, 2020). "Previous work in experimental models of hematologic and solid malignancies have identified CD47 and SIRPα as potential therapeutic targets, whereby blocking this axis (predominantly using anti-CD47 mAb) demonstrated increased phagocytosis of cancer cells by macrophages and M1 polarization." (PMID 33381449, 2020). "Therefore, SG635‐SF had a synergistic effect through the oncolytic adenovirus and CD47 blockade, making it a potent candidate in treating CD47‐positive cancers." (PMID 31899582, 2020). "Indeed, the dual signaling protein SIRPα-4-1BB blocked the interaction of SIRPα with CD47 and induced in vitro neutrophil- and macrophage-mediated phagocytosis of cancer cells." (PMID 33105656, 2020). "Studies showed that microRNAs (miRNAs) encapsulated into liposome-protamine-hyaluronic acid nanoparticles could regulate CD47 expression levels, and results from animal models of solid tumors suggested that they could represent potential cancer strategies." (PMID 32677994, 2020). "Therefore, the side effects of CD47-SIRPα checkpoint inhibitors should be considered if they are applied in clinical practice because angiogenesis is an important factor in cancer cell growth." (PMID 32733941, 2020). "CD47 inhibition leads to stimulation of phagocytosis of cancer cells by macrophages." (PMID 32082311, 2020). "CD47-SIRPα interactions are involved in many cellular processes, including proliferation, apoptosis and immune response as well as the inhibition of macrophage phagocytosis, thereby allowing cancer cells to escape immune surveillance." (PMID 33384022, 2020). "We hypothesized that blocking CD47 on MM cells with mAbs will enhance phagocytosis and killing of MM, which represents a novel strategy for MM cancer immunotherapy." (PMID 32012878, 2020). "Thus, the overexpression of CD47 by cancer cells prevents elimination by myeloid cells and reduces the efficacy of antibody immunotherapy." (PMID 33105656, 2020). "QPCTL inhibitors represent a promising anti-cancer strategy that could potentially avoid the antigen sink of other anti-CD47 drugs due to CD47 expression on erythrocytes and other cells." (PMID 32677994, 2020).